IL23R (interleukin 23 receptor)
Diseases named in the same sentence as IL23R in open-access papers (continued):
Sharing a sentence is not in itself a finding about the gene and the disease.
psoriasis (continued). "Conversely, no notable association was identified between psoriasis and the IL23R SNP, rs11209026." (PMID 40343299, 2025). "The identification of the type I cytokine receptor gene IL23R as genetic risk factor for psoriasis initially was a secondary finding: Variants at IL12B, a gene encoding a subunit shared by the cytokines IL–12 and IL–23, were found to be significantly associated with psoriasis in a GWAS." (PMID 38835412, 2023). "Three of the identified psoriasis risk variants had a stronger association with PsC than PsA (rs12189871 near HLA-C, rs4908742 near TNFRSF9, rs10888503 near LCE3A), whereas two had a stronger association with PsA than PsC (rs12044149 near IL23R, rs9321623 near TNFAIP3)." (PMID 36826011, 2023). "Moreover, sensitization with the inflammatory agent Imiquimod (IMQ), which induces a skin inflammation with common features to psoriasis in an IL-23-dependent manner, increased the frequency of IL-23R-expressing TCRγδ cells, while inducing a small increase of the CD4+IL-23R+ subpopulation." (PMID 32203518, 2020). "A mechanistic link between psoriasis and the circadian clock was suggested by a study in mice which provided evidence that Clock may regulate psoriasis-like skin inflammation in mice via direct modulation of IL-23R expression in γ/δ + T cells." (PMID 27231897, 2016). "We also confirm association of PsA with a previously reported psoriasis locus, NOS2, bringing the total number of confirmed, genome-wide significant, PsA loci to 10 including 4 that are PsA-specific (HLA-B, chromosome 5q31, PsA-specific variants within IL23R and now PTPN22)." (PMID 25923216, 2015). "Increased IL23R was found in psoriasis skin, and anti-IL23R could improve the psoriasis." (PMID 23840241, 2013). "The IL-23/Th17 axis (IL23R, STAT3) is already targeted in IBD by monoclonal antibodies such as ustekinumab (IL-12/23p40) and risankizumab (IL-23p19), initially developed for psoriasis and later repurposed for Crohn’s disease and ulcerative colitis." (PMID 41154835, 2025). "We examined the expression of cytokines previously reported to be involved in psoriasis, and found that IL17A, IL17F, IL26, CCL20, CXCL13, IL22, and IL23R were specifically expressed by Tc17 cells." (PMID 37308489, 2023). "There also exists common genetic abnormalities (chromosomal locus 6p21, IL23R, and IL12B), immune dysfunction, and inflammation (IL17), or gut dysfunction of disease progression both in both psoriasis and ulcerative colitis." (PMID 36106326, 2022). "Finally, in the interleukin 23 receptor (IL23R) gene, the IL23R rs11209026 polymorphism has shown an influence on the response to anti-TNF drugs in naive patients and on the risk of developing toxicity and/or paradoxical psoriasis through the anti-TNF treatment." (PMID 34577605, 2021). "In psoriasis, epidermal CD8+ TRM cells express CLA, CCR6, CD103 and IL-23R antigen and produce IL-17A during ex vivo stimulation." (PMID 31963581, 2020). "Interestingly, a number of conditions display mixed characteristics of both autoimmunity and autoinflammation e.g. Behçet’s disease (BD), inflammatory bowel disease (IBD), ankylosing spondylitis (AS) and psoriasis, where IL-23R may be a factor in disease pathogenesis." (PMID 30054427, 2018). "Seven of these have previously been reported for psoriasis (MHC, TRAF3IP2, IL12B, IL23R, IL23A-STAT2, TNIP1, TYK2)." (PMID 25651891, 2015). "It has been shown that the IL-23R gene plays an important role in the pathogenesis of some autoimmune diseases, such as IBD, AS, psoriasis, rheumatoid arthritis, and multiple sclerosis." (PMID 26678098, 2015). "Only one locus, IL23R, demonstrated true independence of the psoriasis SNP; the PsA-associated SNP rs12044149 remained highly significant (P=2.4 × 10−14) after conditioning on the psoriasis SNP, rs9988642, and the addition of rs9988642 did not improve the model fit with LRT (P=0.21)." (PMID 25651891, 2015).
psoriasis (continued). "Recently, a genome-wide scan study in 1,409 psoriasis cases and 1,436 controls revealed associations between three genes of the IL-23 pathway (IL23A, IL23R and IL12B), two genes of nuclear factor-κB (NF-κB) pathway (TNIP1 and TNFAIP3) and psoriasis." (PMID 21555979, 2011). "The IL-23R gene plays a crucial role in IBD (IBD17) and psoriasis (PSORS7) pathogenesis." (PMID 39364475, 2024). "Furthermore, psoriasis-related factors, such as IL-17A, IL-17F, IL-22, and IL-23R, can be transcriptionally activated by STAT3, suggesting that STAT3 plays a promoting role in psoriasis development." (PMID 36835162, 2023). "Taking the example of psoriasis, skin with clinically resolved psoriasis was demonstrated to contain increased IL-17 mRNA expressing CD103+CD8+ TRM, and an enrichment of IL-23 responsive CD103+CCR6+IL23R+CD8+ T cells." (PMID 33669367, 2021). "The results of GWAS suggest that there are PsA-specific genetic variants which are independent of those previously identified in isolated psoriasis, specifically near IL23R and TNFAIP3 (TNFα Induced Protein 3)." (PMID 33574815, 2020). "Moreover, SOC1, IL-12B, IL-23R, TRAF3IP2 and IL23A have been found to be related to the pathway involved in Th17 cell differentiation in psoriasis." (PMID 29232931, 2017). "We noted that the PsA study index SNP is not always highly correlated with the reported psoriasis index SNP; notable examples include IL23R, TYK2 and NOS2A loci (r2<0.2)." (PMID 25651891, 2015). "In this respect, studies started to evaluate SNP in IL-23R, showing that perturbations in IL-23 signaling pathways lead to pathophysiological changes which may be the ground for the development of autoimmune diseases such as MS, IBD, psoriasis, RA and AS." (PMID 35011777, 2021). "Systemic IL-23 overexpression induced local inflammation in the enthesis by triggering resident IL-23R+RORγt+CD3+CD4−CD8− lymphocytes to secrete IL-17 and IL-22, ultimately leading to IL-17-dependent enthesitis, IL-22-dependent bone remodeling as well as aortic root inflammation and psoriasis." (PMID 29922283, 2018). "In addition, rs610604 (TNFAIP3) and rs17728338 (TNIP1), but not rs2066808 (IL23R) and rs397211 (IL1RN), were associated with psoriasis in a case-control study." (PMID 24069534, 2013). "Hence, the IL23R and IL12B loci appear to be associated with psoriasis and PsA but not with inflammatory arthritis in the form of RA." (PMID 19035472, 2008). "They made a study on a smaller number of pediatric IBD patients, suggesting that IL23R genes (rs10489628, rs10789229, and rs1343151) were more prevalent in patients with psoriasis after infliximab therapy than CD patients treated also by infliximab but who did not develop psoriasis." (PMID 39000125, 2024). "Therefore, it is possible that increased frequency in IL-23R+ T cells may be a specific characteristic of SLE but not psoriasis." (PMID 21110900, 2010). "However, most reports on the links between psoriasis and increases in cells or molecules of the IL-23/Th17 axis focused on psoriatic skin lesions, and the report on increase in circulating Th17 in psoriasis did not use IL-23R but other markers to identify the Th17 population." (PMID 21110900, 2010). "Moreover, a decrease in IL-23R expression was observed as the BSA increased; this may be due to the fact that the BSA scale assesses only the extent of psoriasis, but not its severity, as it does not take into account the morphological features (infiltration, scale and erythema) of lesions." (PMID 34945130, 2021).
Crohn disease (89 papers, 2007 to 2026). A gastrointestinal disorder characterized by chronic inflammation involving all layers of the intestinal wall, noncaseating granulomas affecting the intestinal wall and regional lymph nodes, and transmural fibrosis. "In inflammatory autoimmune conditions, CAR-Tregs targeting the interleukin-23 receptor (IL-23R) effectively suppressed pathogenic Th17 cell responses and attenuated colitis in preclinical models of Crohn’s disease (CD)." (PMID 41050649, 2025). "Genetic variations in the tumor necrosis factor ligand superfamily member 15 (TNFSF15) and interleukin 23 receptor (IL23R) genes, both involved in suppressing inflammation, have been associated with an increased risk of developing Crohn’s disease." (PMID 40392591, 2025). "Genome-wide studies have revealed an association of Crohn’s disease with the IL-23 signaling pathway through the IL-23 receptor (IL23R), thereby emphasizing an essential role of IL-23 in the pathogenesis and manifestation of IBD." (PMID 41235222, 2025). "Despite extensive genome-wide association studies identifying over 200 loci associated with IBD, such as NOD2, ATG16L1, and IL-23R, these genetic variants account for only a fraction of the heritability observed in Crohn’s disease (CD) and UC." (PMID 41007813, 2025). "At the genetic level, individuals carrying IL23R, a Crohn’s disease risk gene, had a decreased abundance of microbes related to Christensenellaceae, indicating that the gut microbiome was influenced by host genetics." (PMID 37444223, 2023). "The IL23R gene has been associated with inflammatory bowel diseases (IBD) including Crohn’s disease and ulcerative colitis." (PMID 37081571, 2023). "In their study apoptosis-resistant intestinal TNFR2 + IL23R+ T cells were associated with resistance to anti-TNF therapy in Crohn’s disease." (PMID 36384462, 2022). "The A allele of rs11209026, a low-frequency IL-23R variant, was negatively correlated with Crohn's disease." (PMID 33324152, 2020). "Only one SNP associated with Crohn’s disease and ulcerative colitis, rs76418789 (IL23R Gly149Arg), was significantly associated with sarcoidosis (P < 0.05) in both our Japanese discovery and replication cohorts." (PMID 32826979, 2020). "In a genome-wide association study in 2006, IL-23R was significantly associated with Crohn's disease, an inflammatory bowel disease." (PMID 33324152, 2020). "Of interest, Arg381Gln, an uncommon allele at a highly conserved amino acid polymorphism, confers a protective effect in patients with Crohn's disease or ulcerative colitis through modulating IL-23R recycling and cytokine production by macrophages." (PMID 31886308, 2019). "GWAS has identified numerous single-nucleotide polymorphisms (SNP) in IL-23R, with high association for Crohn's disease and ulcerative colitis." (PMID 31886308, 2019). "Other genetic associations include IL-10 and IL-23R, which are notably also implicated in Crohn’s disease (CD), ulcerative colitis (UC) and AS." (PMID 30054427, 2018). "Polymorphisms in the gene encoding the IL-23 receptor (IL-23R) are important susceptibility factors for Behcet’s disease, ankylosing spondylitis, and IBDs like Crohn’s disease and ulcerative colitis." (PMID 29508278, 2018). "Genetic variants of the IL-23R gene are protective for Crohn's disease and ulcerative colitis, suggesting that the IL-23 receptor function is to suppress the immune system." (PMID 29230082, 2017). "Our objective was to assess the frequency of ATG16L1 (T300A) and IL23R (L310P) variants in Moroccan IBD (Crohn’s disease and Ulcerative Colitis) patients and to evaluate a possible effect of these variants on disease’s phenotype and clinical course." (PMID 25159710, 2014).
Crohn disease (continued). "Recent targeted deep re-sequencing experiments in Crohn’s disease patients and healthy controls have identified further protective variants in the IL23R." (PMID 24586521, 2014). "Polymorphisms in IL23R have been associated with Crohn’s disease, rheumatoid arthritis and ankylosing spondylitis, and variants of IL10 have been associated with ulcerative colitis and systemic lupus erythematosus." (PMID 24286189, 2013). "This idea was later supported by case-control studies, which associated genetic variants in IL23R with susceptibility to Crohn's disease, psoriasis and ankylosing spondylitis." (PMID 22359581, 2012). "The SNPs in the IL-23R gene region display particularly strong association and significantly reduce the risk of developing Crohn’s disease." (PMID 21994779, 2011). "Analysis for gene-gene interaction with CEACAM6.and IL23R variants regarding susceptibility to Crohn's disease (CD)." (PMID 21559399, 2011). "R381Q (rs11209026), the only coding IL23R variant identified by GWAS, confers an OR of 0.45 for Crohn's disease development (MAF 1.9% in CD, 7% in controls), and an OR of 0.55 for UC development (MAF 3.7% in UC, 7% in controls), implying a protective effect." (PMID 22022372, 2011). "An inverse relationship between a genetic polymorphism of its surface IL-23 receptor (IL-23R) and Crohn's disease has been described." (PMID 21806815, 2011). "IL23R shows association not only with AS, Ps, PsA, but also with inflammatory bowel disease and paediatric Crohn's disease." (PMID 21281511, 2011). "These are perhaps the most expected given the association of IL23R and other pathways ultimately affecting interleukin signaling to Crohn's disease." (PMID 20584322, 2010). "The risk and protective haplotypes associated with Crohn's disease and ulcerative colitis in the Swedish population were identical to those found in the first reported association of IL23R with IBD." (PMID 19175939, 2009). "Our study is the first to report association of IL23R with Crohn's disease and ulcerative colitis in Swedish patients with IBD." (PMID 19175939, 2009). "A notable example is the association between a loss-of-function missense variant in IL23R gene and Crohn’s disease, suggesting that IL-23 blockage could be beneficial." (PMID 39563277, 2024). "However, when mice were supplemented with C. minuta, the IL23R-protective coding variant was reported to increase, thereby protecting against Crohn’s disease." (PMID 37444223, 2023). "Summary of Asian studies for the association of IL23R with Crohn's disease (CD) susceptibility." (PMID 31799225, 2019). "It is suggested that IL-23/IL-17 axis and single nucleotide polymorphisms (SNPs) of IL23R may have crucial role in pathogenesis of Crohn’s disease (CD)." (PMID 31052515, 2019). "In addition, IL23R gene showed a protective effect for individuals with the TT genotype and T allele against the development of Crohn’s disease." (PMID 25159710, 2014). "Specifically, it was demonstrated that the Glu allele at residue 381 in the IL-23R protein conferred significant protection against developing Crohn’s disease and ulcerative colitis, while other genetic variants in this gene, in contrast, conferred increased risk." (PMID 24586521, 2014). "In contrast to the L310P polymorphism in IL23R gene, which confers protection to individuals with the TT genotype and T allele against the development of Crohn’s disease, with respective odds ratio 0.26 (CI: 0.01-5.19, P = 0.38) and 0.74 (CI: 0.31-1.73, P = 0.48)." (PMID 25159710, 2014). "At the common susceptibility gene IL23R, coding for interleukin-23 receptor for Crohn disease, low-frequency variants have been identified as protective factors, and their effects turned out to be larger than those of common variants and accounted for a greater portion of genetic contribution." (PMID 22513239, 2012).
Crohn disease (continued). "Interestingly, the WNT genes above had comparable gene score before and after conditioning; however, the effect of IL23R was able to mask their association to Crohn's disease." (PMID 20584322, 2010). "The CD161+CD39+ co-expression pattern appears particularly effective for identifying Th17-enriched populations, with these cells displaying characteristic Th17 markers (CCR6, IL-23R) and serving as useful indicators of Th17 activity in Crohn’s disease." (PMID 40895554, 2025). "The IL23R expression has been found to be elevated in the intestinal tracts of patients with Crohn’s disease." (PMID 41235222, 2025). "IL23R also plays a significant role in diseases such as: ankylosing spondylitis, Crohn’s disease, psoriatic arthritis, ulcerative colitis, Vogt-Koyanagi-Harada disease (VKH), and more recently, leprosy." (PMID 41430577, 2025). "For example, researchers have recently developed a novel strategy by engineering Tregs to express a chimeric antigen receptor targeting the interleukin-23 receptor, thereby generating IL-23R CAR-Tregs as a potential therapy for Crohn’s disease." (PMID 40959055, 2025). "A growing body of evidence indicates that the IL-23/IL-23R axes play a pivotal role in the pathogenesis of inflammatory bowel diseases, including Crohn’s disease (CD) and ulcerative colitis (UC), as well as colon cancer." (PMID 39796684, 2024). "Genome-wide association studies have revealed that IL23R and five additional genes involved in Th17 differentiation (IL12B, JAK2, STAT3, CCR6 and TNFSF15) are associated with susceptibility to Crohn’s disease." (PMID 36498596, 2022). "Spondyloarthritis shares several genetic risk factors with Crohn’s disease, including TNF family and IL23R genes, and patients have an increased risk of developing colitis." (PMID 31227842, 2019). "For instance, PTVs in CARD9, RNF186 and IL23R provide protection against Crohn’s disease and/or ulcerative colitis and PTVs in ANGPTL4, PCSK9, LPA, and APOC3 protect against coronary heart disease." (PMID 29691392, 2018). "The loci identified included SNPs in immune response genes linked to autoimmune diseases including Crohn’s disease, ulcerative colitis, multiple sclerosis, and T1D (CD5, CCL2, IL23R, CD86, HLA, C11ORF30-LRRC32, CLEC16A)." (PMID 29454391, 2018). "TLR9(T1237C) expression also has increased prevalence in Crohn’s disease, particularly among those with NOD2 mutations and IL23R variants." (PMID 26361369, 2015). "We observed the association between Crohn’s disease and NOD2 (rs17313265, 0.28 in CD, 0.19 in controls, OR 1.5, p = 9×10−6) and IL23R (rs11209026, 0.026 in CD, 0.0.071 in controls, OR 0.4, p = 3.8×10−4)." (PMID 25259511, 2014). "One hundred fourteen participants from the general population were genotyped for ATG16L1 (T300A) and IL23R (L310P) along with 69 Crohn’s disease patients (25 women and 44 men) and 30 UC patients (14 women and 16 men)." (PMID 25159710, 2014). "Our results also identify significant association to the valine to isoleucine substitution at position 362 (Val362Ile) in IL23R (P = 1.18×10−03; OR = 0.79 [0.68–0.91]) previously reported by a recent re-sequencing of positional candidates in Crohn's disease." (PMID 24068945, 2013). "We have recently performed a pooled next-generation sequencing study in Crohn's disease, and identified association to novel low-frequency and rare protein altering variants in NOD2, IL23R, and CARD9, as well as IL18RAP, CUL2, C1orf106, PTPN22 and MUC19." (PMID 24068945, 2013). "Analysis for gene-gene interaction of IL12B with IL23R and STAT4 variants, respectively, regarding susceptibility to Crohn's disease (CD)." (PMID 22479607, 2012). "IL23R is the highest ranked known Crohn's disease gene in each of the data sets and it is present in 29 of the pathways used in our analysis." (PMID 20584322, 2010). "This study confirms the very strong involvement of IL-23R and, to a lesser extent, IL-12B, in Crohn's disease in New Zealand." (PMID 21253534, 2010).